FOXO1 (forkhead box O1)
Diseases named in the same sentence as FOXO1 in open-access papers (continued):
Sharing a sentence is not in itself a finding about the gene and the disease.
periodontitis (continued). "Activated in periodontitis by the protein kinase B (AKT)/Forkhead box O1 (FoxO1) axis, DCs play both protective and destructive roles through activation of the acquired immune response." (PMID 34868054, 2021). "Therefore, we hypothesized that in periodontitis, periodontal tissue damage caused by excess oxidative stress response, inflammatory immune response, and impaired osteogenesis can be accomplished by a decrease in the activity of FOXO1." (PMID 33860060, 2021). "The role of FoxO1 in promoting antioxidant defense suggests FoxO1 as a candidate target of periodontitis treatment." (PMID 31781234, 2019). "It indicated that FoxO1 plays an anti-inflammatory role in periodontium regeneration in periodontitis treatment." (PMID 31781234, 2019). "Here, we shed new light on the role of FoxO1 in antioxidant defense and osteogenesis to resist adverse environments in periodontitis." (PMID 31781234, 2019). "Studies of FOXO1 function in dendritic cells demonstrate that FOXO1 protects against bacteria induced periodontitis through upregulation of dendritic cell activity." (PMID 31849924, 2019). "FoxO1 is involved in the recruitment of dendritic cells and the activation of adaptive immunity in periodontitis." (PMID 31781234, 2019). "Targeted deletion of Foxo1 in the dendritic cells has been studied in a mouse model, in which periodontitis was induced by oral inoculation with P. gingivalis and Fusobacterium nucleatum." (PMID 29163477, 2017). "Serum 8-OHdG and FOXO1 levels were similar in periodontitis and control groups (p > 0.05)." (PMID 38658396, 2024). "Accordingly, FOXO1 levels, whose antioxidant effect is known, could be expected to be higher in periodontitis groups." (PMID 38658396, 2024). "In this study, we tested the hypothesis that the FOXO1 may regulate antioxidant mechanisms in periodontal inflammation and aimed to evaluate the salivary and serum FOXO1 and 8-OHdG levels in advanced periodontitis patients." (PMID 38658396, 2024). "The relevant genes that were involved in the PI3K/AKT pathway activation observed in the T2DM-related periodontitis included those that affect apoptosis (e.g., FOXO1, BCL2, and growth differentiation factor 15 [GDF15]) and cell cycle passage (e.g., CDKN1B and CCND1)." (PMID 38241313, 2024). "The role of FOXO1 in supporting antioxidant defense may suggest that FOXO1 is a candidate target for periodontitis treatment." (PMID 38658396, 2024). "All these results suggest that FOXO1 is a therapeutic target for periodontitis." (PMID 37644500, 2023). "FOXO1 was generally expressed at low levels in clinical samples from patients with periodontitis." (PMID 37644500, 2023). "A study reported that the newly discovered lncRNA ENST00000446358 (lncRNA-POIR) in PDLSC of patients with periodontitis mutually inhibited miR-182 and regulated the target gene of miR-182, forkhead box protein O1 (FoxO1), Inhibit the Wnt pathway, thereby enhancing the osteogenic effect." (PMID 36439972, 2023). "Thus, this study contributed new insight into the anti-inflammatory capability of FoxO1 and provided new evidence for tissue regeneration in periodontitis treatment." (PMID 31781234, 2019). "However, more in vitro and in vivo studies are needed to confirm the role of FoxO1 in the immune system and osteogenesis to promote tissue regeneration in periodontitis." (PMID 31781234, 2019). "Moreover, lncRNA POIR was demonstrated to form a regulatory network with miRNA182 and FoxO1 to up-regulate PDLSC osteogenic differentiation in periodontitis patients." (PMID 29197342, 2017). "However, whether FoxO1 contributes to antioxidant defense and osteogenesis to promote tissue regeneration in periodontitis remains unclear." (PMID 31781234, 2019). "This study aimed to evaluate the salivary and serum FOXO1 and 8-OHdG levels in Stage III periodontitis patients." (PMID 38658396, 2024). "Therefore, FOXO1 may be a potential target for the treatment of periodontitis." (PMID 37644500, 2023).
periodontitis (continued). "In the present study, we found that the interaction of the transcription factors FOXO1 and STAT3 mediated periodontitis-related lipopeptide FSL-1-induced ITGB6 downregulation in human epithelial cells." (PMID 36299623, 2022). "Based on the hypothesis that FOXO1 may regulate antioxidant mechanisms in periodontal inflammation, we evaluated and compared saliva and serum samples obtained from SIIIGB and SIIIGC with non-periodontitis healthy controls." (PMID 38658396, 2024). "Therefore, the interaction of FOXO1 and STAT3 may contribute to periodontitis progression by inhibiting ITGB6 expression." (PMID 36299623, 2022). "To confirm the role of FOXO1 and STAT3 and its relation to ITGB6 expression in vivo, we performed immunohistochemistry to detect the expression of ITGB6, FOXO1, and STAT3 using sequencing slices from healthy human gingival tissue and gingival epithelium of patients with periodontitis." (PMID 36299623, 2022).
sarcopenia (19 papers, 2017 to 2025). Progressive decline in muscle mass due to aging which results in decreased functional capacity of muscles. "FoxO1 and FoxO3a proteins transcriptionally upregulate the expression of the muscle-enriched E3 ubiquitin ligase associated with sarcopenia, including muscle RING finger 1 and muscle atrophy F-box." (PMID 36147639, 2022). "Although previous studies employing FoxO1/3/4 triple-knockout and Atrogin-1-deficient cells have established the critical role of the FoxO3–Atrogin-1/MuRF-1 axis in acute muscle atrophy, its causal relevance in naturally occurring chronic sarcopenia remains undefined." (PMID 41568005, 2025). "In skeletal muscle, FOXO1 upregulates atrophy-related genes such as Atrogin1 and MuRF1, thereby promoting muscle protein degradation and contributing to sarcopenia." (PMID 41282482, 2025). "Numerous studies suggest a positive role of vitamin D in sarcopenia prevention or inhibition of muscle atrophy by suppression of forkhead box protein O1 (FOXO-1) transcriptional activity." (PMID 33799389, 2021). "Similarly, in sarcopenia, oxidative stress contributes to the activation of FOXO1 and FOXO3, driving the muscle protein ligase pathway and autophagic activity." (PMID 41509286, 2025). "Moreover, a strong correlation between SIRT6 and FOXO1 (r=0.82, p<0.001) mRNA levels was observed in the group of patients with sarcopenia, in contrast to the geriatric controls (r=0.35, p=0.089)." (PMID 40034697, 2025). "Recently, the IRS1/Akt/FoxO1 signaling pathway was reported to appear in sarcopenia." (PMID 29271915, 2017). "Notably, a study on sarcopenia, the physiological age-related loss of muscle mass, identified FOXO3 as an up-regulated gene in muscles from old subjects and another study found increased FOXO1 mRNA in aged muscle." (PMID 29529088, 2018). "The findings demonstrated that FOXO1, CTH, HSD11B1, GSTK1, and SPTSSA were the five sarcopenia model genes (SMGs) that were included in the LASSO regression model." (PMID 41325398, 2025). "Identifying these 13 ERSRCGs including FOXO1, KAT2A, and CTH brings attention to the central contribution of ER stress in the development of IPF and sarcopenia." (PMID 41325398, 2025). "Correspondingly, the sarcopenia model showed marked differential expressions of BCL6, DDIT4, FLNA, FOXO1, NFKBIA, PGK1, and STAT3." (PMID 41282482, 2025). "LASSO regression identified CTH and IDI1 for IPF, and FOXO1, CTH, HSD11B1, GSTK1, and SPTSSA for sarcopenia." (PMID 41325398, 2025). "Meanwhile, DDIT4, FOXO1, and STAT3 exhibited significant differential expressions in the sarcopenia dataset GSE362." (PMID 41282482, 2025). "In muscle, FoxO1 activation by ROS downregulates glucose transporter type 4 (GLUT4) and induces atrophy programs (Atrogin-1/MuRF1), impairing glucose uptake and promoting sarcopenia." (PMID 41037185, 2025). "The hypothesis is that genes involved in epigenetic modifications, such as SIRT1, SIRT3, SIRT6, FOXO1, FOXO3A, DNMT3A, and ELAVL1, are critical for the development of sarcopenia and could be used as biomarkers for the diagnosis and monitoring of the disease." (PMID 40034697, 2025). "Furthermore, we observed increased expression of SIRT3, SIRT6, FOXO1, and ELAVL1 in patients with sarcopenia compared to the geriatric controls and the frailty group, although these differencesdid not reach statistical significance." (PMID 40034697, 2025). "Neither study found a significant difference in expression of FOXO1 between COPD patients with sarcopenia and COPD patients without sarcopenia." (PMID 31498843, 2019). "However, the two studies that perfomed a sub-analysis did not observe any significant differences in FOXO1 expression in COPD cases with sarcopenia versus COPD cases without sarcopenia." (PMID 31498843, 2019).
endometriosis (18 papers, 2013 to 2025). The growth of functional endometrial tissue in anatomic sites outside the uterine body. "Taken together, these findings indicate that NEK2 regulates the development of endometriosis and associated disorders of decidualization through the phosphorylation of FOXO1, providing a new therapeutic target for its treatment." (PMID 38795132, 2024). "Collectively, these studies demonstrate that reduced FOXO1 expression and the associated defective decidualization in eutopic endometrium of endometriosis patients results from multiple dysregulated pathways, including impaired Notch signaling and enhanced CAPN7 and NEK activity." (PMID 40072055, 2025). "Likewise, hampered Notch signaling in mice is linked to the development of endometriosis which contributes to dysdecidualization through the down-regulation of FOXO1, which might lead to subsequent implantation failure." (PMID 36776897, 2023). "Downstream progesterone-responsive genes, such as HOXA10, IGFBP1, and FOXO1, are also affected by DNA methylation and histone modifications, and are altered in endometriosis." (PMID 41009686, 2025). "To verify the effect of the FOXO1 Ser184 on the biological significance of endometriosis cells, we conducted a rescue experiment." (PMID 38795132, 2024). "Studies have revealed that patients with endometriosis have a low FOXO1 expression level, and multiple genes affect decidualization of endometrial stromal cells by regulating FOXO1." (PMID 38795132, 2024). "Our study lays a theoretical foundation for developing new strategies for the treatment of endometriosis and its associated endometrial decidualization defects by targeting NEK2 and FOXO1." (PMID 38795132, 2024). "Bushen Wenyang Huayu Decoction, a compound Chinese medicine preparation, inhibits autophagy by up-regulating SIRT1 (Sirtuin 1) and down-regulating FoXO-1 (Forkhead box protein O) expression in endometriosis via the SIRT1-FoXO-1 signaling pathway." (PMID 38397379, 2024). "NEK2 promoted the proliferation, migration, and invasion of endometriotic cells and impaired the decidualization of endometriosis eutopic endometrial stromal cells by phosphorylating FOXO1 at Ser184 and reducing its stability." (PMID 38795132, 2024). "For example, Notch signaling pathway activity is reduced in decidualized endometrial stromal cells from patients with endometriosis, and this pathway impairs decidualization through downregulation of FOXO1." (PMID 38795132, 2024). "Forkhead Box O1 (FOXO1) level in endometriosis was 1.6 times lower in the early secretory phase (15-21 days) than in the normal group." (PMID 36532015, 2022). "The expression of the pioneer transcription factor FOXO1 is reduced in both the endometrium and stromal cells from lesions of women with endometriosis." (PMID 31387263, 2019). "A recent study also showed that inhibition of the v-akt murine thymoma viral oncogene homolog (AKT)-mediated signaling pathway impaired development of endometriosis and restored PR and FOXO1 expression in ectopic lesions." (PMID 27776183, 2016). "IGFBP-1 is downregulated in endometriosis via reduced levels of forkhead box O1 (FOXO1) and homeobox A10 (HOXA10), upstream target genes of IGFBP-1." (PMID 24179489, 2013). "In endometriosis, multiple pathways converge to disrupt FOXO1 function." (PMID 40072055, 2025). "Additionally, NEK2 is upregulated in both eutopic and ectopic endometrium from endometriosis patients compared to controls, correlating with decreased FOXO1 levels." (PMID 40072055, 2025). "Moreover, NOTCH1 silencing reduced FOXO1 expression more markedly in ESCs from endometriosis patients compared to controls, indicating that impaired Notch signaling contributes to decidualization defects through FOXO1 downregulation." (PMID 40072055, 2025). "Notably, exogenous BMP2 treatment restored the expression of the downregulated decidualization markers IGFBP1 and FOXO1 in both eutopic (endometriosis) ESCs and epithelial assembloids." (PMID 40072055, 2025).
endometriosis (continued). "In endometriosis FOXO1 was phosphorylated by the phosphatidylinositol 3 kinase (PI3K)/protein kinase B (AKT) signaling pathway and degraded by ubiquitination after exiting the nucleus, resulting in decreased expression of the downstream decidualization marker IGFBP1." (PMID 38795132, 2024). "Our findings demonstrated that NEK2 and FOXO1 were negatively correlated in endometriosis." (PMID 38795132, 2024). "Previous data showed the same trend with lower FOXO1 levels expressed in endometriosis, which might contribute to an overactive PI3K/AKT pathway, but the underlying mechanisms are not well understood." (PMID 29357938, 2018). "However, the regulatory mechanisms by which FOXO1 decreases and affects decidualization in endometriosis remain unclear." (PMID 38795132, 2024). "The evidence from cellular experiments suggests that NEK2 directly interacts with FOXO1 and phosphorylates at the Ser184 site inhibits the protein stability of FOXO1, thereby enhancing proliferation, migration, invasion and impairing decidualization of stromal cells in endometriosis." (PMID 38795132, 2024). "Molecular and genetic evidence has indicated multiple regulatory pathways by which decidualization defects might arise, and many have been identified as aberrant in endometriosis, including estrogen, progesterone, forkhead box O1 (FOXO1), AKT, and Notch pathways." (PMID 36195592, 2022). "To measure the levels of endogenous FOXO1 protein, we overexpressed or knocked down NEK2 in endometriosis cells." (PMID 38795132, 2024). "Calpain7 promotes nuclear exclusion of FOXO1 by hydrolyzing AKT serine/threonine kinase 1 (AKT1) and inhibits decidualization of human endometrial stromal cells in endometriosis." (PMID 38795132, 2024). "This study revealed the increase of NEK2 in endometriosis compared to controls, and NEK2 was negatively correlated with FOXO1." (PMID 38795132, 2024). "We next analyzed the expression levels of SOX4, PGR, FOXO1, HERC4, IGFBP1, and PRL in the mid-secretory endometrium of healthy women (control, n = 12) versus women who suffered RIF due to endometriosis (EMS-RIF, n = 12)." (PMID 35244538, 2022). "Some decidualization-related genes are downregulated in both the endometriotic lesions and endometrium of women with endometriosis—HOXA10, forkhead box O1 (FOXO1), Indian hedgehog signaling molecule (IHH), and CCAAT/enhancer-binding protein-beta (C/EBPbeta)." (PMID 34833476, 2021). "The top five key regulators in the miRNA-TF-gene network of endometriosis were FOXC1, FOXO1, miR-182-5p, miR-106a-5p, and CEBPA, which were directly connected to 117, 64, 57, 49, and 49 corresponding targets, respectively." (PMID 29357938, 2018). "Here, we identified four important FOX subfamily members, FOXO1, FOXC1, FOXL1 and FOXJ1, which cooperatively regulate the integrative networks in endometriosis." (PMID 29357938, 2018). "However, since FOXO1 is also regulated by PGR, it is difficult to conclude which molecule becomes dysregulated first in endometriosis based on the current literature." (PMID 31387263, 2019).